FAP (fibroblast activation protein alpha)
Diseases named in the same sentence as FAP in open-access papers (continued):
Sharing a sentence is not in itself a finding about the gene and the disease.
tumor (continued). "Since the NB cells that were used for tumor implantation were found to be FAP-negative and we could not detect CAFs in the primary tumor tissue, we hypothesized FAP’s role by tumor-infiltrating leukocytes." (PMID 36230765, 2022). "Tumor-promoting CAFs and tumor-restricting CAFs are likely mixed, even in a single clinical tumor, and this balance within a PDAC could be modified by several CAF-targeted approaches (i.e., Hedgehog inhibitors and anti-FAP agents), which may lead to altered clinical outcomes." (PMID 35805064, 2022). "Those preliminary findings may trigger future studies in the context of radioactive FAP-directed therapies, as higher tumor load or uptake may not lead to decreased doses in the majority of normal organs." (PMID 35681588, 2022). "FAP-IL2v treatment did not affect VAP-1 expression on the tumor vasculature." (PMID 35874707, 2022). "Since FAP is overexpressed mainly in CAFs and not in tumor cells, the tumor cell-line transfected with human or murine FAP could not reflect the tumor microenvironment." (PMID 34556528, 2022). "However, we believe that our results are still informative as the lack of other components does not impact the specific expression of FAP either by CAF or tumor cells." (PMID 36178531, 2022). "68Ga-FAPi-46 SUVs and immunohistochemistry scores were higher in cancer than in tumor-adjacent non-cancer tissue: mean SUVmax 7.7 versus 1.6 (P < 0.001), mean SUVmean 6.2 versus 1.0 (P < 0.001), and mean FAP immunohistochemistry score 2.8 versus 0.9 (P < 0.001)." (PMID 34740953, 2022). "Interestingly, FAP could be clearly detected by the CD45 cell population, suggesting a role for FAP as a target in the tumor microenvironment expressed by tumor-infiltrating leukocytes." (PMID 36230765, 2022). "However, FAPi PET human biodistribution in cancer has not been validated against tumor FAP expression as assessed by immunohistochemistry in a pancancer approach." (PMID 34740953, 2022). "In light of the evidence of prostate-specific membrane antigen (PSMA) overexpression in tumor cells and fibroblast activation protein (FAP) upregulation in the tumor stroma, heterodimer dual targeting PSMA and FAP may have the potential to improve tumor diagnosis." (PMID 35337180, 2022). "Together, these findings imply that FAP+ fibroblasts and SPP1+ macrophages contribute to ECM remodeling and coordinate to form a desmoplastic microenvironment that prevents lymphocytes infiltrating the tumor core, further reducing the efficacy of PD-L1 treatment." (PMID 35365629, 2022). "Those preliminary findings may trigger future studies to determine possible implications for “hot” theranostic approaches and “cold” FAP-directed drugs, as one may expect an unchanged dose for normal organs even in patients with higher tumor load." (PMID 35681588, 2022). "Moreover, it is noteworthy that FAP and SPARC gene expression analysis in primary BCAFs and paraffin-embedded BC tissues showed that our in vitro tumor stromal microenvironment could be comparable to in vivo tumor stromal microenvironment." (PMID 35743318, 2022). "FAP degrades denatured collagens and participates in tumor growth via a non-enzymatic mechanism." (PMID 35745648, 2022). "Without CMS1 tumours, the discriminative power of FAP expression further increased to 0.94." (PMID 35296803, 2022). "However, the current therapeutic paradigm focuses on tumor-stroma interactions in PAAD rather than the expression of FAP protein." (PMID 36263225, 2022). "Therefore, the nanoplatforms containing ligands targeting FAP and PSMA, such as 177Lu2O3-iFAP, 177Lu2O3-iPSMA, or even hybrid 177Lu2O3-iFAP/iPSMA systems could improve tumor retention due to their specific binding to both fibroblasts and tumor neovasculature." (PMID 35456554, 2022). "Only 1 metastasis contained identifiable tumour cells without clear FAP expression." (PMID 35296803, 2022).
tumor (continued). "Those preliminary findings may trigger future studies to determine possible implications for treatment with radioactive FAP-targeted drugs, as higher tumor load or uptake may not lead to decreased doses in the majority of normal organs." (PMID 35681588, 2022). "However, the tumor-promoting and immunosuppressive activity of FAP+ fibroblasts have been demonstrated to suppress TNF signaling, thereby contributing to cancer–stroma–cancer interaction loop that promotes tumor progression." (PMID 36263225, 2022). "Among these FAPα activatable theranostic pro-photosensitizers, FAP-MB-5 with N,N-dimethylglycine blocked N-terminal structure could be specifically and effectively activated by recombinant human FAPα (rhFAPα) and FAPα-expressed tumor tissues." (PMID 35664057, 2022). "PS1 silencing reduced the expression of FAP and αSMA on CAFs and reduced tumour burden in an ovarian tumour mouse model via increased CTL infiltration, indicating that PS1 has a significant role in CAF mediated T cell exclusion from the tumour nest, likely upstream via promoting CAF activation." (PMID 35479076, 2022). "PERTINENT FINDINGS: In this translational study using TMA and an interim analysis of a prospective exploratory imaging trial in 15 surgical oncology patients, the FAPi PET uptake and FAP expression per immunohistochemistry correlated strongly in cancer and tumor-adjacent non-cancer tissue." (PMID 34740953, 2022). "Thus, we were curious about whether the enhanced tumor uptake and retention of 177Lu-TEFAPI-06 and 177Lu-TEFAPI-07 are FAP-dependent." (PMID 34593598, 2022). "Because TMAs may not always be representative of the entire tumor, heterogeneity of FAP expression is a major issue." (PMID 35818720, 2022). "This may be the result of tumor heterogeneity, since FAP displays CAFs and FDG tumor metabolism." (PMID 35771317, 2022). "The huge difference between the two molecules can be explained by the high specific recognition of FAP-α to M1, which was conducive to efficient molecular tailoring and assembly in tumor, while the M2 was non-specific cleavage and accumulation in liver during metabolism." (PMID 35058435, 2022). "Pre-CD10 was related to tumor size (p=0.032), while pre-FAP was not (p=0.413)." (PMID 36387219, 2022). "Orthotopic implantation of 0.5 × 106 cells from four different FAP+ cell cultures in immunodeficient mice (2–3 per each culture) did not lead to neurological symptoms and tumour formation in any of the animals after a median follow-up of 98.5 days (range 85–140)." (PMID 34282761, 2021). "They further discovered that these FAP+/PDGFRβ+ cells participated in TGFβ secretion in GBM, which is consistent with previous studies showing that GBM-activated pericytes secrete high levels of immunosuppressive cytokines, including IL-10 and TGFβ, and promote tumor growth." (PMID 34068501, 2021). "Compared with non-tumor fibroblast (NF) or peri-tumor fibroblast, CAFs are located more proximal to the neoplastic region and exhibit a greater activation marker, namely actin smooth muscle (αSMA) and fibroblast activation protein (FAP)." (PMID 34760886, 2021). "For example, one study revealed that FAP-specific CAR T-cells did not regulate tumor growth and might instead induce lethal osteotoxicity and cachexia by killing pluripotent stem cells in the bone marrow stroma." (PMID 34490078, 2021). "Flow cytometric analysis also revealed the presence of FAP in B16-F10 tumour tissue resected from mice, but not in B16-F10 cells cultured in vitro, supporting the notion that the B16-F10 tumour stroma contains FAP+ CAFs." (PMID 33299131, 2021). "One study that combined anti-FAP CAR T cells along with total body irradiation and IL-2 injections showed limited anti-tumor efficacy as well as enhanced side effects including bone marrow toxicity and cachexia in numerous tumor types such as those of the head and neck, lung, and pancreas." (PMID 34200702, 2021).
tumor (continued). "The high and rather selective tumour uptake of very promising FAP-targeting tracers as described opens up applications for non-invasive tumour characterization, staging examinations, and radioligand therapy in many different cancers with a high content of activated fibroblasts." (PMID 33806468, 2021). "FAP inhibitors introduced via bifunctional DOTA and DOTAGA chelators offer the possibility to complex Lutetium-177 due to an additional coordination site, and are suitable for theranostic applications owing to the increased tumor accumulation and prolonged tumor retention time." (PMID 34959613, 2021). "Research has shown that in the absence of T cell-activating immunotherapy, high counts of FAP + MAFs accumulate in the tumor stroma and this may serve as a negative prognostic marker." (PMID 32328671, 2021). "Continuing the clinical assessment of the radiolabeled FAP-based inhibitors, FAPI-21 and FAPI-46—the other two outstanding FAPI derivatives that developed in an attempt to improve FAPI-04 performance—indeed, showed superior tumor accumulation and tumor-to-background ratios over FAPI-04." (PMID 34681246, 2021). "The cytokine levels also did not change in response to the decrease in FAP+ cells, which supports the latter hypothesis that FAP reduces the response of tumor cells to tumor necrosis factor alpha and IFNγ." (PMID 34490078, 2021). "Fibroblast activation protein (FAP) is highly expressed in many epithelial carcinomas, and various isotope-labelled fibroblast activation protein inhibitors (FAPI) show lower uptake in the brain and abdominal tissues than in tumor, thus achieving high image contrast and good tumor delineation." (PMID 35059319, 2021). "Furthermore, FAP was found to be coexpressed with CD90 on tumor cells, which has been demonstrated to drive GBM cell invasion, suggesting that FAP might promote cell invasion via functional interactions with CD90." (PMID 34068501, 2021). "Moreover, FAP can form complexes with DPPIV, matrix metallopeptidase 1, matrix metallopeptidase 2, urokinase-type plasminogen activator, and other proteins, which can act as inter-cell signal transduction pathways to promote tumor cell invasion." (PMID 34490078, 2021). "Presence of FAP on the cell surface of CAFs could be confirmed by IHC in all tumor specimens while it was absent in reactive, tumor-free lymph nodes." (PMID 34050405, 2021). "Moreover, using the TIDE (Tumor Immune Dysfunction and Exclusion) database, we found that ITIH1 expression was also negatively correlated to T cell exclusion signatures, including FAP+ CAFs, myeloid-derived suppressor cells (MDSC), and tumor-associated M2 macrophages (TAM M2)." (PMID 33744857, 2021). "Those proteins have been tested in preclinical studies showing promising results; for instance, the fusion protein sc40-FasL was tested against tumor stroma in mice by intravenous administration, showing no signs of systemic toxicity and preventing the growth of FAP-positive cells." (PMID 33801589, 2021). "According to existing data, inhibiting FAP enzyme activity may have some beneficial effects on the tumor microenvironment, but it may not be sufficient to prevent tumor progression." (PMID 34490078, 2021). "Thus, FAP-positive cases at the centre of the tumour were also significantly higher in non-organ-confined tumours and in pT2 tumours than in pT1 ones." (PMID 33207686, 2020). "In the treatment of murine melanoma, ablation of FAP-expressing stromal cells induced a reduction in immuno-suppressive myeloid cells, although it is likely that this was related to paracrine effects rather than alteration in the tumour ECM." (PMID 33187209, 2020). "Notably, and similar to the situation in most tumor types, FAP staining is distinctly absent from the actual HT-29 cancer cells within the tumors." (PMID 32728930, 2020).
tumor (continued). "Recent publications have described a more ubiquitous expression of FAP in murine models of cancer, and since murine and human FAP share 89% sequence homology including the catalytic active site, we expected to observe reduced tumor-to-non-target tissue contrast in our in vivo imaging studies." (PMID 32806623, 2020). "This is not very surprising, since many of the FAP enzymatic products are signaling molecules involved in immune suppression and FAP also has unknown tumor growth modulating functions that are irrespective of its enzymatic activity." (PMID 32316521, 2020). "Thus, sFAP levels from patients with FAP negative RCCs were similar to patients with FAP positive tumours." (PMID 33207686, 2020). "However, only a certain subpopulation of CAFs expresses FAP and it is completely absent in other tumor fibroblast subpopulations." (PMID 33333727, 2020). "Our observation that FAP+ and αSMA+ cells are distinct in GBM is in accord with our knowledge that CAFs in cancer are highly heterogenous in marker status and function, and suggests that mesenchymal stromal cells in the GBM tumor microenvironment are also heterogenous." (PMID 33308315, 2020). "Another critical emphasis was to know whether bispecific targeting of liposomes with HER2’scFv together with FAP specific scFv would influence HER2’scFv based binding, and if the liposomes would deliver cargos into the nuclei of tumor cells in vivo similar to trastuzumab-targeting liposomes." (PMID 33076292, 2020). "This is in contrast to our data demonstrating targeting FAP was ineffective in combination with anti-PD1 and radiation, which may be due, in part, to FAK inhibition repolarizing tumor cytokines not seen with FAP inhibition." (PMID 30726287, 2019). "However, in the tumor center, we did not detect FAP and CD31 in three tumors and in one tumor, respectively." (PMID 30922247, 2019). "It is also hypothesised that the biological effects of FAP may be more prominent in smaller tumours or earlier stages of CRC, not in late-stage metastasis." (PMID 31289350, 2019). "However, FAP targeting alone or with tumor-directed radiation did not improve survival even when combined with anti-PD1 therapy." (PMID 30726287, 2019). "When comparing FAP KO tumor bearing animals who received anti-βgal T cells to those who received tolerized FAP KO T cells (closed circle vs closed triangle and closed square vs closed diamond), there was no tumor growth delay or survival benefit." (PMID 30726287, 2019). "Moreover, we have also demonstrated that the depletion of FAP-positive stromal cells from the tumor mass enhances the overall antitumor efficacy without increasing the toxicity." (PMID 30683154, 2019). "Both expression and nuclear translocation of EGR1 were reduced in F4/80+ TAMs in Il6−/− tumours, suggesting that loss of nuclear EGR1 expression might be responsible for the reduction of FAP expression by TAMs in the absence of IL-6." (PMID 30054470, 2018). "In the same model FAP-IL2v further enhances the efficacy of PD-L1 checkpoint inhibition when combined with an agonistic CD40 antibody resulting in long term survival in the majority of animals, and in the induction of immunological memory as evidenced by protection from tumor cell re-challenge." (PMID 30400822, 2018). "Partial toxin‐induced depletion of FAP+ CAFs, as well as pharmacological blockage of CXCL12 signaling by inhibiting its receptor C‐X‐C chemokine receptor 4 (CXCR4), reduced tumor growth and enhanced T cell accumulation within the tumor, thus sensitizing tumors to α‐PDL1 treatment." (PMID 29280568, 2018). "Interestingly, high tumor uptake of 68Ga-FAPI-02 was observed in mice bearing FAP-expressing (HT-1080-FAP) as well as FAP-negative (Capan-2) cancer cell lines because of recruitment and activation of mouse fibroblasts." (PMID 29626120, 2018).
tumor (continued). "However, this did not result in the presence of FAP+ macrophages in these tumours, indicating that FAP+ TAMs are not directly derived from this G-CSF-induced myeloid population." (PMID 30054470, 2018). "There was no inter-tumour correlation of the TAM’s expression of FAP and tumoral Col1a1 expression." (PMID 30054470, 2018). "We found that the plasma FAPα was not correlated with the FAPα expressed in tumor, and the multi-organ might contribute to the circulating levels of FAPα including skeletal muscle, liver and bone marrow." (PMID 28415791, 2017). "Treatment of the samples with free EpCAM BiTE and the EpCAM BiTE‐expressing viruses led to strong T‐cell activation (measured by CD25 expression), and a depletion of EpCAM‐positive tumour cells to background levels, although FAP‐positive (EpCAM‐negative) fibroblasts showed no change in numbers." (PMID 28634161, 2017). "As previously detailed, our primary cell cultures were negative for markers of hematopoietic cells (CD45), tumor-associated macrophages (CD163), activated hepatic stellate cells (GFAP), endothelial cells (CD31), fibroblast-activation protein (FAP), and stromal-derived factor (SDF1)." (PMID 28873435, 2017). "In addition, we compared the plasma FAPα level before and after tumor resection and found not significant difference between them." (PMID 28415791, 2017). "Targeting of each of the IgG-IL2v molecules (CEA-IL2v, FAP-IL2v, and DP47-IL2v) to the various compartments of the 3D heterotypic spheroids was assessed using 100 nM of fluorescently labeled molecules CEA-IL2v penetrated the spheroid and remained targeted to the tumor cell compartment." (PMID 27858101, 2017). "Thus, FAP can remodel the ECM and influence tumor cells’ growth by promoting angiogenesis." (PMID 27834810, 2016). "The expression of mutated Braf within the B16 tumor cells may have affected levels of FAP+ cells, as a different B16.F10 tumor with wild-type Braf but modified to express GFP had markedly higher percentages of FAP+ cells (~ 25%, data not shown)." (PMID 26943036, 2016). "In both tumor models frequencies of TAMs were not affected by the FAP vaccine." (PMID 26943036, 2016). "The disappointing clinical outcome of Val-boroPro does not exclude the potential role of FAP α's proteolytic activity in tumor invasion and metastasis, or that an inhibitor antibody may be a potent therapeutic target." (PMID 26985769, 2016). "Because FAP is expressed in CAFs, but not in the tumor cells used in this study, we hypothesize that the observed tumor inhibition may have occurred, in part, due to CAF-mediated modulation of the immune TME and direct antitumor immunity." (PMID 26394925, 2015). "Finally, the role of FAP interactions with the tumor environment was not assessed in this analysis because the original data from the selected studies did not contain such information." (PMID 25775399, 2015). "It was reported that a monoclonal anti-FAP antibody conjugated to maytansinoid induced a long-lasting inhibition of tumor growth and complete regression in different experimental tumor models, without signs of toxicity." (PMID 25474039, 2015). "Removing FAPα+ fibroblasts does not alter the number or subtypes of tumor infiltrating T cells, but does result in their activation and secretion of interferon-γ (IFN-γ) and tumor necrosis factor-α (TNF-α), two antitumor cytokines secreted by activated Th1 and NK cells." (PMID 26305550, 2015). "Although the effect of cancer on the muscle ECM and collagen network are not well defined, fibroblast activation protein-α (FAP)-positive stromal cells are significantly reduced in skeletal muscles of C26 tumor-bearing mice and depletion of these cells is sufficient to induce muscle fiber atrophy." (PMID 25539728, 2014). "Using the scFv as an active targeted fragment against the tumor stroma marker, the fibroblast activation protein (FAP) and the scTNF-lpNPs could specifically bind to FAP expressing cells and hardly bind to FAP-negative cells." (PMID 25268623, 2014).